CD163 (CD163 molecule)
Diseases named in the same sentence as CD163 in open-access papers (continued):
Sharing a sentence is not in itself a finding about the gene and the disease.
tumor (continued). "Macrophage markers (CD68 and CD163) were immunohistochemically determined in formalin fixed paraffin-embedded slides containing the primary tumor and surrounding adipose tissue." (PMID 40940394, 2025). "Flow cytometry revealed that 1,25(OH)2D3 treatment significantly increased CD163 level in co-xenograft tumor (p < 0.001)." (PMID 40453717, 2025). "M2 TAMs, characterized by a CD68+/CD163+ phenotype, release cytokines that deplete tumor-infiltrating lymphocytes (TILs), inactive killer T cells and facilitate tumor immune evasion." (PMID 40539047, 2025). "How CD163 expression changes during tumor progression, the prognostic value and potential relevance of the tumoral localization of CD163+ immune cells in metastatic tissue remain uncharacterized." (PMID 39751847, 2025). "Another study depicted the prognostic impact of studying CD8(+), FOXP3(+), and CD163(+) cell density separately in the tumor center and the invasive front, stressing the significance of considering immune cell distribution." (PMID 40243442, 2025). "In vivo, we observed the upregulation of IRF9, p‐PI3K, p‐AKT, and CD163 in subcutaneous tumor tissues from nude mice injected with ITGβ8‐overexpressing A549 cells." (PMID 39535362, 2025). "Tumor-associated macrophages in the tumor microenvironment express a number of markers, such as CD163, indicating an M2-like polarization state of macrophages with tumor-protective functions." (PMID 39936166, 2025). "In SRC, the immune microenvironment affected CS tumor growth, depletion of T lymphocytes resulted in increased tumor growth rates, while depletion of CD163+ macrophages delayed tumor progression." (PMID 40004005, 2025). "DS decreased the number and the size of metastatic tumor nodules in nude mice while decreasing CD163 expression." (PMID 41142606, 2025). "Cardamonin reduced pro-tumor activity of TAMs, decreased M2 markers (CD163, CD206), and suppressed IL-6, VEGFα, MMP2, MMP9 secretion." (PMID 40330466, 2025). "This study evaluated the clinical significance of the proportion of the hepatoid component within the tumor, CD163 + macrophages, and macrophage colony-stimulating factor-1 (CSF-1) in HAS." (PMID 39488822, 2025). "In parallel, increased expression of the M2 macrophage markers CD163 and Fizz1 suggests a shift toward an immunosuppressive microenvironment that favors tumor growth." (PMID 41304988, 2025). "We also found that MGAT1 OE in tumor cells enhanced a tumor-promoting M2-like phenotype in TAMs, usually defined by the expression of CD163 and MHC II." (PMID 40229283, 2025). "Alternatively, activated macrophages (M2) stimulate angiogenesis and suppress immunity around tumor cells by expressing CD163 on their surface." (PMID 39857069, 2025). "The immunohistochemistry for detecting components of the tumor microenvironment reveled the infiltration of tumor-associated macrophages (CD68, CD163) and tumor-associated fibroblasts (vimentin, SMA) in the tumor sample." (PMID 40433378, 2025). "Another study showed increased infiltration of both NOS2+ M1 and CD163+ M2 macrophages in the invasive tumor front (TF)." (PMID 40508145, 2025). "After neoadjuvant chemotherapy, CD163(+) macrophages increase in tumor tissues, and M2 TAMs reduce the sensitivity of EC cells to cisplatin." (PMID 39678502, 2024). "We subsequently tested the epithelial membrane antigen (EMA), vimentin, CD68, and CD163 in tumor tissues, all of which showed positive expression." (PMID 39432588, 2024). "Precisely, metformin produced a decrease in tumor-promoting CD163+ macrophages and an increase in tumor-suppressive CD11c+ macrophages, in CD8+ cytotoxic T lymphocytes and CD20+ B lymphocytes." (PMID 38659591, 2024). "We observed a rise in MALAT1 expression, correlating with increased levels of monocyte chemoattractant protein-1 (MCP-1) and CD68, CD163, CD206, indicative of tumor-associated macrophages in lung tumors of AA patients." (PMID 38791954, 2024).
tumor (continued). "CD163 TAMs were positively associated with a higher tumor grade, while CD206 TAMs were associated with smaller tumor size in triple-negative breast cancer (TNBC)." (PMID 38893266, 2024). "Immunohistochemistry identified significantly reduced Ly6G+ TAN and CD163+ M2 TAM stainings on primary tumor sections from anti-CHI3L1- compared to IgG control-treated mice, and add-on reductions of both markers in chitin-treated primary tumors." (PMID 38605414, 2024). "Collectively, our data suggest that TME-derived signals, including IL-3 and M-CSF, induce CD163+ TAMs to proliferate within tumours as they differentiate from their monocytic precursors." (PMID 38903497, 2024). "Since MIP-1β is produced by macrophages, the correlation between MIP-1β and the density of macrophages (CD68 and CD163) in the tumor microenvironment was evaluated." (PMID 38339307, 2024). "Increased CD163+ macrophage infiltration in tumor stroma positively correlated with higher tumor grade, larger tumor size, Ki67 positivity and ER/PR negativity." (PMID 39044824, 2024). "Second, tumoral tissues are often enriched with immune suppressive cells such as CD68+CD163+ macrophages and T regulatory cells, and we show that tumor cells spatially surround themselves with immune suppressive cells." (PMID 38575670, 2024). "Baseline expression of CD8, CD68, CD163, PD-1, PD-L1 and regulatory T cells (Treg) in the tumor microenvironment was evaluated with clinical outcome." (PMID 38339307, 2024). "Specifically, we examined the presence of CD4+, CD8+, CD20+, CD68+, and CD163+ cells within the tumor microenvironment." (PMID 38288307, 2024). "A high expression of CD163 in tumor-sparse regions suggested the potential presence of CD163+ M2 type macrophages/monocytes, which supports the results from the deconvolution analysis." (PMID 39001353, 2024). "We examined CD4, CD8, CD68 and CD163 cells for analysis of the tumor microenvironment in both intratumoral and stromal compartments, as well as the overall number of tumor microenvironment cells." (PMID 39123373, 2024). "Treatment notably decreased CD68 + CD163 + macrophages in biopsies from tumor lesions compared to pre-treatment samples in 9 of the 28 patients after 4 weeks." (PMID 38374062, 2024). "For patients in cohorts from Huashan Hospital, the density of M2-like TAM was calculated by IHC staining with CD163 in the tumor slides." (PMID 38291499, 2024). "In OM and PT area, CD163+ cells looked smaller and were observed in the tumor capsule, inside lymphatics, along sinusoids as well as in the stroma of portal spaces." (PMID 38287290, 2024). "In this study, CD163 showed significant higher expressions with larger tumor size, higher histological grade and advanced stage group." (PMID 39462379, 2024). "Consistently, in the pancreatic cancer model, CD86+IRF5+M1 TAMs were closer to the tumor cells than CD163+CD206+M2 TAMs." (PMID 38279145, 2024). "This showed that tumor tissues in mice treated with hypoxic cancer cells sEVs had increased in volume, weight, and CD163 expression." (PMID 38690261, 2024). "We first analyzed M2 macrophage markers, such as Arg-1, IL-10, and CD163 in tumor and paracancer tissues." (PMID 38822362, 2024). "The mRNA expression of Arg-1, IL-10, and CD163 were markly up-regulated in tumor samples compared to paracancer tissue samples." (PMID 38822362, 2024). "We observed colocalization of IDO1, PD-1, CD68 (marker of TAMs), and CD163 (marker of M2 macrophages) in the tumour stroma." (PMID 39351094, 2024). "CD68 and CD163 expression varied across tumor sections, with some showing strong positivity and others resembling atypical ALK-rearranged histiocyte-rich tumors." (PMID 39867882, 2024). "The prognostic value of CD68+CD163+ TAMs was assessed in the tumor nest and stroma of TNBC patients." (PMID 39044824, 2024). "Kaplan–Meier analysis revealed that patients with high CD163 expression had a poor prognosis in the tumor detected by IHC (P < 0.001)." (PMID 38714539, 2024).
tumor (continued). "In particular, a lower CD163+ macrophage count was found in tumor samples of patients who responded to immunotherapy." (PMID 38740647, 2024). "The expression of specific TAMs, such as CD47, CD68, and CD163, has been studied in NPC and is linked to various aspects of tumor behavior, prognosis, and potential therapeutic strategies." (PMID 39682556, 2024). "Of note, the tumor-adjacent adipose tissue of obese patients showed a substantially larger increase of CD163+ macrophages (3.7-fold) than for CD68+ (1.7-fold) as compared to normal-weight TNBC patients." (PMID 39456610, 2024). "Tumor-promoting genes such as CD163 and CD209 were highly expressed in the myeloid cells, and depletion marker genes such as TIGIT, LAG3 were highly expressed in NK/T cells." (PMID 38582791, 2024). "Supporting an increased immune response, we found higher numbers of CD68+ and CD163+ (M2-like) macrophages in the tumor-adjacent adipose tissue of overweight/obese TNBC patients." (PMID 39456610, 2024). "The immunosuppressive role of the CD163+ macrophages in tumors highlights the anti-inflammatory role of the tumor microenvironment, which leads to tumor growth and poor clinical outcomes." (PMID 39451197, 2024). "Tregs and CD163+macrophages had a higher tendency to infiltrate into the tumor center compared with B cells, CD8+T cells and CD4+T helper cells." (PMID 39053947, 2024). "RG7155 potently inhibited the viability of CSF-1-differentiated macrophages in vitro and reduced the number of CD68+ CD163+ TAMs in tumor biopsies from diffuse-type giant cell tumor patients." (PMID 39516356, 2024). "They measured tumor volume and weight in different groups using a mouse model and detected CD163 expression in the tissues using IHC." (PMID 38690261, 2024). "PD-L1 expression correlated with the presence of CD8+T cells irrespective of their location, showing a stronger correlation in the tumor center, with CD68+ macrophages only in the tumor center and with CD163+ macrophages only at the tumor margin." (PMID 39338178, 2024). "Elimination of CD163-expressing TAMs triggered T cell infiltration and tumor regression, implying the role of paracrine TAM-derived tumor-promoting mechanisms." (PMID 39451197, 2024). "A high ratio of CD163/CD68 in tumor stage MF and SS suggests M2 polarization of TAMs, which is associated with tumor advancement." (PMID 39703508, 2024). "Immunohistochemistry revealed infiltration of CD8-positive T cells and CD163-positive macrophages in the tumor stroma." (PMID 38514507, 2024). "When analyzing the total number of cells in the tumor and tumor-adjacent adipose tissue together, only CD163+ cells were significantly more abundant in overweight/obese patient (4.06-fold; p = 0.039)." (PMID 39456610, 2024). "In this case, the tumor demonstrated a significant immune response with high levels of CD163 (3+), CD68 (3+), PDL-1 (2+), CD3 (3+), and CD8 (3+) infiltrating cells." (PMID 39335193, 2024). "CD163 showed significant higher expressions with larger tumor size, higher histological grade and advanced stage group." (PMID 39462379, 2024). "As CD163 is a universal marker for macrophages infiltrated in iCCAs and its expression indicates alternative macrophage polarization with a tumor-permissive phenotype, we attempted to confirm its universally spatial distribution in our data." (PMID 39256888, 2024). "Following immunotherapy, tissue samples from all HP patients exhibited tumor infiltration by M2-like CD163+, CD33+, PD-L1+ luster-forming epithelioid macrophages and enrichment of TAM." (PMID 39034998, 2024). "Our data raised the possibility that CD163+ TAMs that originate from blood monocytes expand within tumours in response to signals within the TME." (PMID 38903497, 2024). "Among these studies, 13 studies used CD68 as a biomarker for TAM identification in tumor tissue, while five and three studies used CD163 and CD204, respectively." (PMID 38501293, 2024).
tumor (continued). "Several reports on CD163, a marker of tumor-promoting M2 TAMs in carcinomas, indicate that high levels of its expression correlate negatively with prognosis." (PMID 39199574, 2024). "Our finding of increased CAF-like cells in overweight/obese TNBC patients is consistent with the elevated number of CD163+ M2-macrophages in tumor-adjacent adipose tissue observed in these patients." (PMID 39456610, 2024). "By confocal IF and ISH, EGFR overexpression was localized in our cases to not only epithelial cells, as we expected, but also to endothelial cells and infiltrating CD163+ macrophages in the dermis and the lamina propria in tumor-like ORF lesions." (PMID 38613413, 2024). "When cocultured with conditional medium of TNBC cells, a shift of M2 polarization was observed in tumor-associated macrophages characteristic by the elevated expression of CD206 and CD163." (PMID 38169627, 2024). "In contrast, M2 macrophages, characterized by both CD68 and CD163 expression, are considered to promote tumor growth and metastasis by releasing chemokines, which are inflammatory growth factors." (PMID 39594814, 2024). "There was a statistically significant difference in the number of CD8+ T cells and CD163+ M2 macrophages (p = .001 and p = .035, respectively) and in relation to tumor T stage (p = .011 and p = .009 respectively) between resectable and unresectable cases." (PMID 38954689, 2024). "Multiplex immunofluorescence for CD86 and CD163 was performed to directly show the infiltration of macrophages in tumor tissues of 615-line mice." (PMID 38238529, 2024). "Previous studies have highlighted the enrichment of CD163+ macrophages in inflammation and tumor occurrence microenvironments, with anti-inflammatory or anti-tumor drugs targeting CD163+ macrophages showing promising therapeutic effects in animal models." (PMID 39323470, 2024). "The number of CD8+ cytotoxic T cells, as well as CD68+ and CD163+ macrophages, differed significantly between the invasive front and the tumor center." (PMID 39630300, 2024). "CD163, an abundant endocytic receptor for various ligands, is particularly enriched in the inflammatory and tumor microenvironments with CD163+ macrophages." (PMID 39108264, 2024). "The widespread existence of CD163+ M2 polarized macrophages that promote tumor cell proliferation and inhibit T-cell evolution is specific to GBM." (PMID 39594814, 2024). "As GBM immune edits infiltrating myeloid cells and given that CD163/FKBP51s are equally distributed in the two clusters, we investigated the role of the tumor in generating this macrophage phenotype." (PMID 38651817, 2024). "A proximity between clusters of CD163 colonies and an elevation in CD163 adjacent to tumour are independent predictors of poor prognosis in patients after NACT." (PMID 39273252, 2024). "Treatment with MCP led to an increase in CD86 expression and TNF-α secretion, indicative of enhanced M1 polarization, while reducing CD206 and CD163 expression along with IL-10 secretion, thus supporting a shift towards a more anti-tumor immune response." (PMID 39593969, 2024). "Despite this, there was evidence of anti‐tumor activity such as the low number of CD163+ cells, greater necrosis, high levels of IL‐10 and low levels of IL‐6 and IL‐27." (PMID 38600057, 2024). "The findings of this study provide compelling evidence that elevated expression levels of CD47, CD68, and CD163 in tumor tissues are significantly correlated with poorer PFS and OS in patients with NPC." (PMID 39682556, 2024). "And the correlation between CD163+ macrophages infiltration and PD-L1 expression in tumor cells was higher than that of stromal cells." (PMID 38970071, 2024). "The secondary analysis, with “Very low” split into “None” and “Detectable low”, revealed similar trends across the four groups in tumor-infiltrating immune cells, with the CD163 category maintaining statistical significance." (PMID 39272861, 2024).
tumor (continued). "FTH1 was highly expressed in M1 macrophages and tumor cells in various cancers, which was also expressed in CD163+ M2 macrophages in ESCC and HCC." (PMID 38281198, 2024). "Within primary tumor, CD163+ was positively correlated with CD163+MMP9+ (r = 0.751, P = 0.0013) and CD68+CD163+CD206+ (ρ = 0.762, P = 9.7E−4)." (PMID 39373616, 2024). "On the other hand, the abundance of tumor-supportive HLA-DR-/CD163 + M2 type macrophages were increased in untreated groups of YAP overexpressing cohorts compared to PC9 parental tumors." (PMID 38702301, 2024). "In particular, overweight/obese patients displayed 3.73-fold (p = 0.011) more CD163+ M2-like macrophages in tumor-adjacent adipose tissue as compared to normal-weight patients, whereas the number of CD68+ cells was increased by 1.7-fold (p = 0.038)." (PMID 39456610, 2024). "Rep was expressed in the tumor‐adjacent mucosa of 99% of CRC patients (TMA), was histologically associated with CD68+/CD163+ macrophages and was increased in CRC patients when compared to healthy controls." (PMID 36811271, 2024). "IHC analysis of 12 pairs of randomly selected CRC samples showed a positive correlation between the proportion of RUNX1 positive areas and CD68 (P < 0.0001), CD163 (P = 0.0002) positive areas in tumor." (PMID 38419056, 2024). "PB-TAMs coexpressing FKBP51s and PD-L1 testified to necrotic tumor while those coexpressing FKBP51s and CD163, found particularly high in recurrences with callosal infiltration, exhibited active STAT6, a transcription factor related to migration and invasion." (PMID 38651817, 2024). "CD68+CD163+ TAM frequency was studied alongside the frequency of tumor infiltrating lymphocytes (TILs) in TNBC patients." (PMID 39044824, 2024). "Using a seven-color multiplex immunohistochemistry panel we identified tumor cells, CD163+macrophages, B cells, CD8+T cells, CD4+T helper cells and regulatory T cells (Tregs) in treatment-naive surgical resection specimens (n=29) and biopsies (n=18)." (PMID 39053947, 2024). "In the same line, neighborhoods with CD163+macrophages were located across the entire tumor area, in the invasive margin as well as in the tumor center." (PMID 39053947, 2024). "Among them, TAM-APOE represented the tumor-associated macrophages with high expression levels of APOE, CD163, and VSIG4." (PMID 39107908, 2024). "In mice, tumor-infiltrating TAMs generally express F4/80 and M2 TAMs and specifically express CD163, allowing quantification of total macrophage vs. M2 TAMs." (PMID 39338373, 2024). "Investigation into sporadic VS growth has shown a positive correlation between immune cell factors such as CD45 and CD68 expression and tumor size and growth rate, as well as elevated CD163 expression in rapidly growing tumors." (PMID 38817895, 2024). "Formalin-fixed paraffin-embedded (FFPE) tissue sections were stained with fluorescence-labelled primary antibodies targeting CD163 for M2c-like macrophages and PanCK for tumours." (PMID 39267775, 2024). "Using TSA-associated multiplex immunofluorescence, we analyzed the proportion of CD8+ T lymphocytes, CD20+ B lymphocytes, FoxP3+ T regulatory lymphocytes, and CD163+ macrophages in tumor samples prior to immunotargeted therapy." (PMID 38612743, 2024). "Here, the authors used shCD163, an inhibitor of CD163, for the suppression of CD163 along with inhibition of cell proliferation, stemness, and tumor progression." (PMID 39457052, 2024). "Although the treatment targeting CD163+ TAMs promotes tumor regression, the specific interaction mode of TAMs and tumor cells is unclear." (PMID 38419056, 2024). "Lipid-associated macrophages, also known as foamy macrophages, are TAMs that are linked to breast cancer and display an M2-like gene profile, such as CD163 expression, and release different pro-tumor secretory factors." (PMID 39062100, 2024). "Noteworthy, CD8+T cells were located further away from tumor cells compared with CD163+macrophages (82 μm vs 56 μm, respectively, p=0.002)." (PMID 39053947, 2024).